COX17 (cytochrome c oxidase copper chaperone COX17)
Description:
Copper metallochaperone involved in the assembly of cytochrome c oxidase (respiratory chain complex IV, CIV). Binds two copper ions and delivers them to metallochaperones SCO1 and SCO2, which co-chaperone the copper ions to the Cu(A) site on the cytochrome c oxidase subunit II (MT-CO2/COX2), and to metallochaperone COX11 which relays the copper to the Cu(B) site on the cytochrome c oxidase subunit I (MT-CO1/COX1).
Tractability: PROTAC: ubiquitination databases record sites on it; its protein half-life has been measured.
Gene: Protein-coding gene on chromosome 3 (119,654,513 to 119,677,621, reverse strand). Ensembl gene ENSG00000138495.
Subcellular location: Mitochondrion intermembrane space; Cytoplasm
Subcellular location (Human Protein Atlas): Mitochondria
Pathways (Reactome):
Metabolism: Complex IV assembly
Protein localization: Mitochondrial protein import
Gene Ontology:
Molecular function: copper chaperone activity; cuprous ion binding; protein binding; copper ion binding; enzyme activator activity
Biological process: mitochondrial respiratory chain complex IV assembly
Cellular component: cytoplasm; mitochondrial intermembrane space; mitochondrion
Genetic constraint (gnomAD): Loss-of-function variants: 1 observed, 3.44 expected, observed/expected ratio (o/e) 0.29, 90% interval 0.1 to 1.33. That is too few expected variants to judge how well the gene tolerates losing a copy. Missense variants: 51 observed, 50.75 expected, observed/expected ratio (o/e) 1, 90% interval 0.8 to 1.27. Synonymous variants: 19 observed, 20.44 expected, observed/expected ratio (o/e) 0.93, 90% interval 0.65 to 1.36.
Homologues: Orthologues: chimpanzee COX17 (98% identical), macaque COX17 (98% identical), pig COX17 (94% identical), guinea pig COX17 (92% identical), mouse Cox17 (92% identical), rat Cox17 (92% identical), dog COX17 (90% identical), rabbit COX17 (89% identical).
Diseases named in the same sentence as COX17 in open-access papers:
COX17 is named in the same sentence as 31 diseases in open-access papers, as found by Europe PMC text mining. Sharing a sentence is not in itself a finding about the gene and the disease. The quoted sentences say what the papers report.
breast carcinoma (5 papers, 2017 to 2025). "COX17 deletion limits mitochondrial copper deficiency and inhibition of TM on invasion and metastasis of breast cancer cells." (PMID 39676279, 2024). "High expression; Associated with poor prognosis; COX17 contributes to metastasis, recurrence, and tamoxifen resistance of breast cancer." (PMID 39676279, 2024). "High levels of mitochondria‐specific copper chaperone COX17 effectively predict poor prognosis, distant metastasis, recurrence, and tamoxifen‐resistance in breast cancer patients." (PMID 39676279, 2024). "We identified 13 members of the copper transport system associated with the occurrence, progression, and mortality of breast cancer, including SLC31A1, DMT1, ATP7A, ATP7B, MTs, GSH, ATOX1, CCS, COX17, SCO1, SCO2, and COX11." (PMID 39676279, 2024). "Owing to decreased expression of GSK-3, MMP-9, NF-B, and COX17, TUR revealed reduced lung metastasis of breast cancer." (PMID 38723038, 2024). "Similarly, breast cancer is characterized by the overexpression of CTR1, ATP7B, ATOX1, and COX17." (PMID 41516324, 2025).
Alzheimer disease (4 papers, 2019 to 2025). A progressive, neurodegenerative disease characterized by loss of function and death of nerve cells in several areas of the brain leading to loss of cognitive function such as memory and language. "A study finds that lead-induced COX17-regulated mitochondrial copper accumulation exacerbates pathology in Alzheimer’s disease." (PMID 40560886, 2025). "This “Alzheimer’s disease” pathway overlaps with other AV-1451-associated pathways that relate to mitochondrial respiration, electron transport, and oxidative phosphorylation (NDUFS4 & 8, NDUFA6 &7, UQCRQ, & COX17), as well as metabolism (NDUFS4 & 8, NDUFA6 &7, UQCRQ, COX17, & ETHE1)." (PMID 35774552, 2022). "In addition, ATP6V1G3 and COX17 were found to be involved in the oxidative phosphorylation pathway, as well as CASP9 being involved in the Alzheimer's disease and Parkinson's disease." (PMID 33247215, 2020). "In addition, ATP6V1G3 and COX17 were upregulated in the oxidative phosphorylation pathway and CASP9 was downregulated in the Alzheimer's disease and Parkinson's disease pathways in CKD patients." (PMID 33247215, 2020).
lung carcinoma (3 papers, 2013 to 2020). "The expressions of CCS and COX17 are generally higher in lung cancer compared to healthy tissue." (PMID 33271772, 2020). "Overexpression of COX17 might also play a significant role in the oncogenesis of lung cancer." (PMID 33271772, 2020).
acute myeloid leukemia (2 papers, 2023 to 2024). Acute myeloid leukemia (AML) is a group of neoplasms arising from precursor cells committed to the myeloid cell-line differentiation. "Indeed, loss of COX17 has been reported to impair DNA methylation and self-renewal of leukemic stem cells in acute myeloid leukemia." (PMID 38612624, 2024).
Parkinson’s (2 papers, 2020 to 2025). "However, together with NDUFB1, COX17, and ATP5MC1, they were reported as upregulated in patients with Parkinson’s, Alzheimer’s, and Huntington’s diseases." (PMID 41296444, 2025).
colorectal cancer (1 paper, 2023). A primary or metastatic malignant neoplasm that affects the colon or rectum. "According to this study, CD4-CXCL13 T cells clustered in malignant tissues in colorectal cancer and shaped immunosuppressive TME by upregulating COX17, which induced T cell exhaustion and infiltration of Treg." (PMID 38078879, 2023).
gastric cancer (1 paper, 2021). A primary or metastatic malignant neoplasm involving the stomach. "In this study, we found that knockdown of gastrin in gastric cancer cells could result in the overexpression of COX17, COX5B, and ATP5J proteins, elevation of mitochondrial membrane potential, and reduction of ROS production in gastric cancer cells." (PMID 33937399, 2021).
glaucoma (1 paper, 2024). Increased pressure in the eyeball due to obstruction of the outflow of aqueous humor. "In our previous study, we observed a decreasing trend in the expression of key mitochondrial proteins, cytochrome c oxidase copper chaperone (COX17) (3-fold), ATP synthase, and H+ transporting mitochondrial F0 complex (ATP5H), following 2 weeks of IOP elevation in Morrison’s model of glaucoma." (PMID 39684751, 2024).
Intellectual disability (1 paper, 2023). "Fibroblasts from patients with MOF syndrome who have intellectual disability also revealed respiratory defects that could be restored by alternative oxidase, acetylation-mimetic COX17 or mitochondrially targeted MOF." (PMID 37813994, 2023).
iron deficiency (1 paper, 2021). "Hepatic expression of the Cu chaperones antioxidant 1 copper chaperone and cytochrome c oxidase copper chaperone (COX17) was decreased during iron deficiency, while the expression of the genes of zinc metabolism was unaltered." (PMID 33671025, 2021).
ischemia (1 paper, 2023). A hypoperfusion of the BLOOD through an organ or tissue caused by a PATHOLOGIC CONSTRICTION or obstruction of its BLOOD VESSELS, or an absence of BLOOD CIRCULATION. "According to other study, the expression of COX17 was up-regulated in ischemia–reperfusion injury AKI mice which suggests that COX17 plays a role in the development of renal fibrosis." (PMID 37758834, 2023).
malaria (1 paper, 2018). Malaria is a serious and sometimes fatal disease caused by a parasite that commonly infects a certain type of mosquito which feeds on humans. "A human anti-malaria antibody pool was passed consecutively over four affinity resins with recombinant P. falciparum LDH, GAPDH, Cox17 and PMT coupled to the resins." (PMID 29505599, 2018).
metabolic syndrome (1 paper, 2021). A cluster of metabolic risk factors for CARDIOVASCULAR DISEASES and TYPE 2 DIABETES MELLITUS. "Specifically, we identified an increased expression of the miR-224 targets Ndufa11, Cox17, Cox16b1, and Id3 in BAT, which associate with metabolic syndrome and obesity." (PMID 34342596, 2021).
ovarian carcinoma (1 paper, 2022). A malignant neoplasm originating from the surface ovarian epithelium. "Among these dysregulated genes, for example, COX17 plays vital role in the development of TNBC, while SLC31A1 is a key target gene for chemoresistance in ovarian cancer, indicating cuproptosis related genes might also play vital roles in BLCA." (PMID 36211344, 2022).
schizophrenia (1 paper, 2010). A major psychotic disorder characterized by abnormalities in the perception or expression of reality. "In a second experiment, we tested the predicted interaction between clozapine, an FDA-approved drug used primarily to treat schizophrenia, and the yeast protein Cox17." (PMID 20226027, 2010).
triple-negative breast carcinoma (1 paper, 2024). An invasive breast carcinoma which is negative for expression of estrogen receptor (ER), progesterone receptor (PR), and human epidermal growth factor receptor 2 (HER2).
tumor (12 papers, 2019 to 2026). "Our data further demonstrate that LPCAT1 regulates the expression of COX17, suggesting that the promotion of Cytochrome c oxidase activity and tumor bioenergetics by LPCAT1 is mediated through COX17." (PMID 41792107, 2026). "Other genes down-regulated in ATRX-altered tumours included USE1, SULT4A1 and the nuclear-encoded mitochondrial gene COX17." (PMID 38978571, 2024). "Subsequently, we investigated tumor immune microenvironment and pathway activity within the high and low RiskScore groups and screened two hub genes based on this model: COX17 and DLAT." (PMID 38078879, 2023). "Further, we used cell communication analysis to explore the tumor microenvironment remodeling mechanisms of the COX17 and DLAT based on scRNA-seq." (PMID 38078879, 2023). "Subsequently, we performed quantitative reverse-transcription polymerase chain reaction (qRT-PCR) to examine the expression levels of the seven key prognostic genes—CEBPB, TANK, MAT2B, TMEM165, CCDC167, CYFIP1, and COX17—in the CEBPB+CAF prognostic model in the tumor tissues." (PMID 40145099, 2025). "COX17 was expressed in the tumor microenvironment, while DLAT expression levels were low." (PMID 39518128, 2024). "For further discover the function of COX17 and DLAT on TME, we chose a scRNA-seq data set which was collected from tumor tissue and peripheral blood samples of 14 treatment-naïve CRC patients, containing 200,626 cells totally." (PMID 38078879, 2023). "Targeting COX17 and DLAT can also remodel TME and activate anti-tumor immunity, favoring a breakthrough in ICB treatment." (PMID 38078879, 2023). "The expression of COX11, COX17, LIAS, CDKN2A and AOC3 was significantly higher in tumor tissues than in normal tissues." (PMID 38078879, 2023). "First, the IHC results showed higher expression of COX17 and lower expression of DLAT within tumor tissues than normal tissues." (PMID 38078879, 2023). "When survival of HPV+ HNSCC patients with low expression of both COX16 and COX17 in their tumours was compared to survival of patients with high expression of both genes, survival was significantly greater in the COX16 and COX17 double low expression group (p = 0.0015)." (PMID 31968678, 2020). "Tumor immune cell infiltration analysis and clinical validation revealed that PRNP (Prion protein), SNCA (Synuclein alpha), and COX17 (Cytochrome c oxidase copper chaperone COX17) may be closely correlated with immune cell infiltration and ICG expression." (PMID 37153542, 2023).
cancer (7 papers, 2019 to 2025). A tumor composed of atypical neoplastic, often pleomorphic cells that invade other tissues. "The relationship between COX17 and DLAT and overall survival (OS) in 32 cancer patients was analyzed and found that COX17 and DLAT expression were significantly associated with OS in many cancers." (PMID 38078879, 2023). "We also explored the expression of the underlying cancer‐promoting genes within cluster 3; these genes included Cdkn1a, Plaur, Ptgs2, Cox17, Lilrb4q, G0s2, Egr1, and Cxcl2, with previous reports suggesting their implication in increasing cancer progression." (PMID 39113226, 2024). "Among them, COX17 was identified as a potential risk factor in GBM(p<0.001) and CRC(p<0.001), however, in other types of cancer, it possesses a protective function, especially PCPG (p<0.05)." (PMID 38078879, 2023). "Notably, one of these clusters exhibited a significant expression of cancer‐promoting genes, encompassing Cdkn1a, Plaur, Ptgs2, Cox17, Lilrb4q, G0s2, Egr1, and Cxcl2." (PMID 39113226, 2024). "Here, we found the effect of gastrin on the expression levels of COX17, COX5B, and ATP5J proteins that are involved in the mitochondrial respiratory chain, which may reveal one of the important mechanisms of gastrin as a cancer promoting factor." (PMID 33937399, 2021).
infection (2 papers, 2013 to 2016). The state of being infected such as from the introduction of a foreign agent such as serum, vaccine, antigenic substance or organism. "Since the kidney is relatively resilient to changes in metal content compared to other organs, we surmised that changes in Cox1 and Cox17 mRNA levels during infection could either signify kidney injury or infection-triggered shifts in renal copper dynamics." (PMID 27362522, 2016). "At 6 h post infection, the energy metabolism related genes (ATP5G2, COX17, COX5B, GSTP1, NDUFAB1 and NDUFS2) were suppressed." (PMID 23527143, 2013).
cardiovascular disease (1 paper, 2020). "In this pathway, upregulation of COX7B, COX17, and ATP6V1G3 as well as downregulation of COX6A2 and UQCRQ may lead to CKD complications with cardiovascular disease." (PMID 33247215, 2020).
COX17 also shares sentences with these, for which no sentence is quoted: colon cancers (1 paper); COVID-19 (1); degenerative joint diseases (1); energy metabolism disorder (1); genetic disorders (1); glioblastoma (1); head and neck squamous cell carcinoma (1); Huntington disease (1); leukemia (1); metabolic disorders (1); Obesity (1).